FRY (FRY microtubule binding protein)
Description:
Plays a crucial role in the structural integrity of mitotic centrosomes and in the maintenance of spindle bipolarity by promoting PLK1 activity at the spindle poles in early mitosis. May function as a scaffold promoting the interaction between AURKA and PLK1, thereby enhancing AURKA-mediated PLK1 phosphorylation.
Synonyms: C13orf14; bA37E23.1; 13CDNA73; CG003; 214K23.2; bA207N4.2
Tractability: PROTAC: ubiquitination databases record sites on it; its protein half-life has been measured.
Gene: Protein-coding gene on chromosome 13 (31,846,713 to 32,299,125, forward strand). Ensembl gene ENSG00000073910.
Subcellular location: Cytoplasm; Cytoplasm, cytoskeleton, microtubule organizing center, centrosome; Cytoplasm, cytoskeleton, spindle pole
Gene Ontology:
Molecular function: enzyme inhibitor activity
Biological process: cell morphogenesis; neuron projection development; negative regulation of tubulin deacetylation
Cellular component: cell cortex; site of polarized growth; centrosome; cytoplasm; spindle pole
Genetic constraint (gnomAD): Loss-of-function variants: 81 observed, 227.64 expected, observed/expected ratio (o/e) 0.36, 90% interval 0.3 to 0.43. The upper end of that interval is the gene's LOEUF score, 0.43, which puts it in group 1 of 6, group 1 being the genes least tolerant of losing a copy. Missense variants: 2,142 observed, 2,933 expected, observed/expected ratio (o/e) 0.73, 90% interval 0.7 to 0.76. Synonymous variants: 1,064 observed, 1,127.9 expected, observed/expected ratio (o/e) 0.94, 90% interval 0.9 to 0.99.
Homologues: Orthologues: chimpanzee FRY (99% identical), macaque FRY (99% identical), rabbit FRY (97% identical), mouse Fry (97% identical), guinea pig FRY (97% identical), rat Fry (95% identical), dog FRY (91% identical), tropical clawed frog FRY (88% identical). Paralogues in human: FRYL (61% identical).
Diseases named in the same sentence as FRY in open-access papers:
FRY is named in the same sentence as 11 diseases in open-access papers, as found by Europe PMC text mining. Sharing a sentence is not in itself a finding about the gene and the disease. The quoted sentences say what the papers report.
breast carcinoma (6 papers, 2013 to 2025). "Our results also suggested that FRY activity was reduced in human breast carcinoma cell lines as a result of reduced levels or mutation." (PMID 24023717, 2013). "Although we observed a higher level of FRY protein in the MCF-7 breast cancer cell line, our studies showed that the FRY gene is mutated and probably dysfunctional in this cell line." (PMID 24023717, 2013). "Taken together, our observations in human and rat mammary tumor cells are consistent with the possibility that decreased FRY activity and/or function is associated with an increased risk of carcinogenesis." (PMID 24023717, 2013). "Thus, the possibility remains that the human FRY gene encodes a putative susceptibility gene on human Chromosome 13q, and studies are in progress to further define its role in human breast cancer." (PMID 24023717, 2013). "Knocking down LATS1 partially reduced the effects of elevated FRY in inhibiting the growth and proliferation of breast cancer cells." (PMID 31824855, 2019). "Our evaluation of breast cancer cells with enhanced FRY levels provided largely indirect data related to the potential tumor suppressing role of FRY." (PMID 31824855, 2019). "Together, our data suggest that the FRY is required for mammary glands developments during pregnant periods, and affects breast cancer cell growth and proliferation." (PMID 31824855, 2019). "The level of FRY mRNA expression in all breast cancer cell lines evaluated was reduced by at least 40% relative to the non-tumorigenic MCF10A human mammary epithelial cell line." (PMID 24023717, 2013). "FRY is required for mammary gland development and may have a role in the suppression of breast cancer cell growth and proliferation." (PMID 35976950, 2022). "We showed that enhanced FRY significantly altered breast cancer cell morphology, growth and proliferation, suggesting that FRY may play a role in breast cancer development and progression." (PMID 31824855, 2019). "To determine whether FRY's cancer cell suppression effects would resonate across different breast cancer types, we constructed a similar breast cancer cell model based on BT474 human breast cancer cells (named 474FRY and 474Vctrl cells)." (PMID 31824855, 2019). "in vitro experiment, ectopic expression of FRY could alter the morphology and significantly suppress the growth and proliferation of the breast cancer cell lines, MDA-MB-231 (ER-/PR-/HER2-, Basal-like) and BT474 (ER+/PR+/HER2+, Luminal B)." (PMID 31824855, 2019). "Moreover, our in vitro studies show that FRY affects morphology and suppresses the growth and proliferation of breast cancer cells, which is likely related to its interaction with protein kinases and associated signaling pathways." (PMID 31824855, 2019). "We next measured human FRY gene mRNA levels in several human breast cancer cell lines." (PMID 24023717, 2013). "FRY protein levels were decreased in 3 of 4 breast cancer lines evaluated." (PMID 24023717, 2013).
epilepsy (1 paper, 2025). A brain disorder characterized by episodes of abnormally increased neuronal discharge resulting in transient episodes of sensory or motor neurological dysfunction, or psychic dysfunction. "A number of THC target DEGs were also associated with synaptic signaling in the brain, and the onset of epilepsy and intellectual deficits, including RPH3A, KCNQ5, and FRY." (PMID 41402937, 2025).
ovarian carcinoma (1 paper, 2026). A malignant neoplasm originating from the surface ovarian epithelium. "Collectively, these findings suggest that FRY is a macrophage-driven mediator of invasion and underscore its potential relevance in ovarian cancer." (PMID 41677651, 2026). "We observed that conditioned medium from ovarian cancer-stimulated macrophages (OCM) robustly induced FRY expression in ovarian cancer cells." (PMID 41677651, 2026).
cancer (9 papers, 2013 to 2025). A tumor composed of atypical neoplastic, often pleomorphic cells that invade other tissues. "FRY, a key component of chromosome separation in metaphase, inhibits the growth of cancer cells in a Hippo pathway–dependent manner in some malignancies." (PMID 35993362, 2022). "Recently, some studies have suggested a role of FRY in cancer development." (PMID 31824855, 2019). "Transcriptome analysis indicated that the FAT/FRY subtype was characterized by inactivation of the Hippo pathway, hypoxia, chemoresistance, higher infiltration of CD8+ T cells and activated DCs, and a transcriptome similar to that of cancer responders." (PMID 35993362, 2022). "The FCGBP, F13A1, FRY, and TMLHE genes had significantly higher expression in normal tissues than in cancer (P = 2.8e-07, P = 3.3e-14, P < 2.22e-16 and P < 2.22e-16, respectively)." (PMID 40264151, 2025).
tumor (8 papers, 2013 to 2026). "We identified 3 driver genes (FCGBP, GRIN2B, and FRY), and recurrent truncating mutations in FRY impaired its tumor-suppressive function and promoted tumor proliferation." (PMID 35993362, 2022). "We also performed a set of functional assays to confirm that truncating mutations in FRY might dampen its effect as a tumor suppressor." (PMID 35993362, 2022). "Taken together, these results showed that FRY mutations might serve as delayed driver events conferring tumor relapse." (PMID 35993362, 2022). "FRY mutations in subclones might endow tumor survival advantages and drive recurrence, evidenced by the shorter DFS of the subclonal mutant compared with that of wildtype patients." (PMID 34885197, 2021). "Recent studies suggest that NDR kinases may also have tumor suppressor activity, indicating that FRY regulates susceptibility to carcinogenesis by regulating the activity of NDR kinases." (PMID 24023717, 2013). "FRY was usually mutated in a subclonal manner (35/36, FDR = 0.006), detectable on average in 11% of the tumor cells in mutant patients." (PMID 34885197, 2021). "Clinically, elevated FRY levels correlate with advanced tumor stage and poor patient survival." (PMID 41677651, 2026). "To further determine whether FRY's interaction with the Hippo/YAP signaling pathway contributes to the observed FRY's tumor suppressive function, we used a siRNA targeting the LATS1 mRNA and reduced endogenous LATS1 protein levels by about 85% in the 231FRY cells (231FRY/LATS1KD)." (PMID 31824855, 2019). "However, the role of FRY in tumor development and progression remains largely unknown." (PMID 31824855, 2019). "In mammals, FRY suppresses nuclear localization of YAP, a transcriptional coactivator with a role in promoting cell proliferation, and thus, may act as a tumor suppressor." (PMID 35976950, 2022).
neurological disorders (1 paper, 2024). "Our findings taken together with results from other model organisms suggest that a DIP2/FRY/DOPEY/Flippase pathway could be involved in maintenance of neuronal morphology in humans, and that altered activity of this pathway may contribute to neurological disorders." (PMID 38766017, 2024).
FRY also shares sentences with these, for which no sentence is quoted: glioma (1 paper); Intellectual disability (1); laryngeal carcinoma (1); melanoma (1); meningioma (1).